SMARCA2 (SWI/SNF related BAF chromatin remodeling complex subunit ATPase 2)
Diseases named in the same sentence as SMARCA2 in open-access papers (continued):
Sharing a sentence is not in itself a finding about the gene and the disease.
ovarian carcinoma (14 papers, 2018 to 2025). A malignant neoplasm originating from the surface ovarian epithelium. "Loss of EZH-2 antagonists such as ARID1A and SMARCA2/4 leads to the repression of tumor suppressor genes in ovarian cancer." (PMID 41301911, 2025). "BAF is mutated in 20% of human cancers and major components of this enzyme complex like ARID1A and SMARCA2/4 are consistently mutated in specific histologies of ovarian cancer." (PMID 41301911, 2025). "Here, the authors demonstrate that the switch of the SWI/SNF catalytic subunits from SMARCA4 to SMARCA2 drives resistance to EZH2 inhibitors in ARID1A-mutated ovarian cancer cells." (PMID 30297712, 2018). "In contrast, high expression of SMARCA2 was associated to good prognosis in breast and ovarian cancer, lung adenocarcinoma, and liposarcoma datasets." (PMID 29391527, 2018). "Here we show that the switch of the SWI/SNF catalytic subunits from SMARCA4 to SMARCA2 drives resistance to EZH2 inhibitors in ARID1A-mutated ovarian cancer cells." (PMID 30297712, 2018). "Indeed, the BAF components ARID1A and SMARCA2/4 are persistently mutated in ovarian cancer subtypes, and represent promising sensitivities for epigenetic inhibition therapy." (PMID 34213777, 2021). "In addition to ESCC cell models, SMARCA2-deficient colorectal, pancreas and ovarian carcinoma cell lines display SMARCA4 dependency, indicating that the interdependence of SMARCA2 and SMARCA4 is hard-wired and context-independent." (PMID 31406271, 2019). "Small cell carcinoma of the ovary-hypercalcemic type (SCCOHT) is a rare ovarian cancer affecting young females and is driven by the loss of both SWI/SNF ATPases SMARCA4 and SMARCA2." (PMID 39906560, 2025). "In the ovary, high expression of SMARCA2 affects the expression of cell cycle- and apoptosis-related proteins in ovarian cancer cells, increasing their resistance to cisplatin." (PMID 39609317, 2024). "SMARCA2 levels were correlated with good prognosis in published datasets for breast and ovarian cancer, lung adenocarcinoma, and liposarcoma, and in the LIHC and KIRC TCGA cohorts." (PMID 29391527, 2018). "On the other hand, SMARCA2 overexpression was found in human epithelial ovarian cancer." (PMID 34315468, 2021). "Recent research has highlighted that, similar to many other cancers, ovarian cancer is marked by alterations in a range of epigenetic regulators, including EZH2, SMARCA2/4, and ARID1A." (PMID 39605897, 2024). "In recent years, it has become clear that, like the majority of other cancers, many epigenetic regulators are altered in ovarian cancer, including EZH2, SMARCA2/4 and ARID1A." (PMID 34213777, 2021).
prostate carcinoma (14 papers, 2012 to 2025). A carcinoma that arises from epithelial cells of the prostate gland. "This truncated fumaramide handle maintainedrobust degradation of BRD4 and expanded the scope of neo-substratetargets, including CDK4/6, SMARCA2/4, and notably, the androgen receptor(AR) and its therapeutically challenging truncation variant AR-V7in androgen-independent prostate cancer cells." (PMID 40726802, 2025). "Androgen receptor (AR)+ forkhead box A1 (FOXA1)+ prostate cancer cells are exquisitely sensitive to dual SMARCA2 and SMARCA4 degradation relative to normal and other cancer cell lines." (PMID 34937944, 2022). "For example, it has recently been shown that androgen receptor (AR) and forkhead box A1 (FOXA1) expressing prostate cancer cells are sensitive to simultaneous degradation of BAF complex subunits SMARCA2, SMARCA4 and PBRM131." (PMID 36216795, 2022). "The down-regulated CUP mRNAs showed fewer significant overlaps but SHEN_SMARCA2_TARGETS_DN gene set, which depict transcripts that are negatively correlated with SMARCA2 expression in prostate cancer was clearly overlapping with the CUP set." (PMID 25885340, 2015). "Down-regulation of SMARCA2 expression was found in prostate cancer tissues and conferred the proliferation advantage to prostate cancer cells." (PMID 23668334, 2013). "The SHEN_SMARCA2_TARGETS_DN gene set was constructed by examining genes that correlated inversely with SMARCA2 expression in prostate cancer samples." (PMID 22824328, 2012). "We previously reported a highly selective PROTAC degrader targeting both mSWI/SNF ATPase subunits, SMARCA2 and SMARCA4, demonstrating remarkable therapeutic efficacy in various preclinical models of advanced prostate cancer through intravenous administration." (PMID 38557192, 2024). "In this study, we utilized a PROTAC compound, AU-15330, that simultaneously degrades SMARCA4, SMARCA2, and PBRM1 and is toxic in enhancer-addicted prostate cancers." (PMID 37094128, 2023). "Western blot analysis confirmed robust downregulation of direct targets (SMARCA2, SMARCA4, and PBRM1) and specific prostate cancer lineage proteins (AR, ERG, C-Myc, and PSA) after 5 d of AU-24118 treatment, whether administered alone or in combination with enzalutamide." (PMID 38557192, 2024). "This implies that SMARCA4, rather than SMARCA2 or PBRM1, may be the critical target to perturb in the context of prostate cancer therapy." (PMID 38557192, 2024).
small cell carcinoma of the ovary (14 papers, 2016 to 2025). "Approximately half of ovarian clear cell carcinomas (OCCC) carry mutations in the SWI/SNF subunit ARID1A, while small cell carcinoma of the ovary hypercalcemic type (SCCOHT) presents with inactivating mutations of the SWI/SNF ATPase SMARCA4 alongside epigenetic silencing of the ATPase SMARCA2." (PMID 32649682, 2020). "In small-cell carcinomas of the ovary, hypercalcemic type (SCCOHTs), characterized by bi-allelic inactivating mutations of SMARCA4, loss of SMARCA2 expression is frequently observed." (PMID 31406271, 2019).
pancreatic cancer (13 papers, 2016 to 2023). "In the case of pancreatic cancer, the presence of SMARCA2 promoter polymorphisms is associated with poor prognosis for patients with diagnosed cancer rather than specific cancer risk." (PMID 31722744, 2019). "Promoter polymorphisms in the SMARCA2 gene are strongly associated with pancreatic cancer patient survival." (PMID 27999365, 2016). "SMARCA2 plays important roles in cell proliferation, linage specification and development, cell adhesion, cytokine responses, and DNA repair, which was previously implicated in risk and prognosis in lung, esophageal, colon cancer, and pancreatic cancer." (PMID 34315468, 2021). "In addition to a panel of SMARCA2-deficient tested cells, SMARCA2-deficient pancreas carcinoma HuP-T4 cells were dependent on SMARCA4." (PMID 31769422, 2019). "To determine whether the same might extend to other SWI/SNF subunits that we observed to be commonly mutated or deleted in pancreatic cancers, we used RNAi to knockdown SMARCA2 (the alternative enzymatic subunit), ARID1A or ARID1B (DNA targeting/specificity subunits) in normal HPDE cells." (PMID 29515757, 2018). "Another catalytic subunit of SWI/SNF complexes SMARCA2 positively regulates the transcription of miR-302a-3p, which acts as a metastasis-promoting miRNA in pancreatic cancer cells." (PMID 37175555, 2023). "Results revealed that the mRNA levels of SMARCA3, SMARCA4, HELLS were significantly upregulated in patients with pancreatic cancer, while the mRNA levels of SMARCA2 and SMARCAD1 were downregulated." (PMID 34315468, 2021). "In the present review, we summarized the mutations of epigenetic regulators, including ARID1A, SMARCA2, SMARCA4, KDM6A, KMT2C, KMT2D, and BRD4 in GI cancers—in particular, pancreatic cancer—and found these regulators to be frequently mutated." (PMID 31238554, 2019). "In vivo studies using SMARCA2-silenced pancreatic cancer cells showed that mice had improved survival and decreased metastases." (PMID 31769422, 2019). "SMARCA2-downregulated pancreatic cancer cells had increased chemosensitivity to gemcitabine in vitro and in vivo." (PMID 31769422, 2019). "Putative DNA binding subunits ARID1A, ARID1B, and PBRM1, enzymatic subunits SMARCA2 and SMARCA4, and ARID2 have been shown to be mutated in pancreatic cancer." (PMID 27999365, 2016). "ARID1A, ARID1B, PBRM1, SMARCA2, and SMARCA4 are all components of the SWI/SNF complexes, and were shown by genomic sequencing studies to be mutated in pancreatic cancer." (PMID 27999365, 2016). "However, SMARCA2 was found significantly decreased in patients with pancreatic cancer compared with that in the normal samples in Buchholz’s dataset, with a fold change of − 6.555 and a P value of 0.009." (PMID 34315468, 2021). "On the other hand, in pancreatic cancer cells SMARCA2 activates epigenetically STAT3 signaling and may promote metastasis." (PMID 34874980, 2021). "In pancreatic cancer, recent whole genomic sequencing also revealed pathogenic mutations and structural variants in several epigenetic regulator genes including KDM6A, ARID1A, ARID1B, PBRM1, SMARCA2, SMARCA4, and MLL2." (PMID 27999365, 2016). "Therefore, further studies are worth to evaluate the precise roles of SMARCA2 in pancreatic cancer." (PMID 34315468, 2021). "As miR-302a-3p directly targets SOCS5 to boost STAT3 phosphorylation and induce the transcription of STAT3 target genes, SMARCA2 starts the miR-302a-3p/SOCS5/STAT3 signaling axis and thus potentiates pancreatic cancer metastasis." (PMID 37175555, 2023).
Coffin-Siris syndrome (12 papers, 2012 to 2022). Coffin-Siris syndrome (CSS) is a rare congenital multi-systemic genetic disorder characterized by aplasia or hypoplasia of the distal phalanx or nail of the fifth digit, developmental delay, intellectual disability, coarse facial features, and other variable clinical manifestations. "Similarly, in another study, SMARCA2 (BRM) was mutated in 43% of patients with Coffin–Siris syndrome." (PMID 25774356, 2014). "The current EpiSignTM BAFopathy episignature encompasses several subtypes of Coffin–Siris syndrome associated with multiple genes (ARID1A, ARID1B, SMARCB1, SMARCA4) and Nicolaides–Baraitser syndrome (SMARCA2)." (PMID 36430143, 2022). "The same corresponding mutations occurring in SMARCA1, SMARCA4, and SMARCA2 (components of a closely related chromatin remodeling complex known as SWI//SNF) cause Schimke immune-osseous dysplasia, Coffin–Siris syndrome and Nicolaides–Baraitser syndrome." (PMID 33981601, 2021). "Very recently, several helicase domain containing Snf2 proteins, including SMARCA2 and SMARCA4, were identified to cause Nicolaides-Baraitser syndrome and Coffin-Siris syndrome." (PMID 22888405, 2012). "Later published studies discovered the etiology of the phenotypically related Coffin-Siris syndrome to be caused by similar mutations in SMARCB1 and ARID1B, which are direct interaction partners of SMARCA2 in the SWI/SNF chromatin remodeling complex." (PMID 23013645, 2012). "By contrast, SMARCA2 duplication rather than mutations is characteristic for Coffin–Siris syndrome." (PMID 31722744, 2019). "Mutations in other genes involved with the SWI/SNF complex such as ARID1A, SMARCA2, SMARCA4, SMARCB1 and SMARCE1 are also responsible for Coffin-Siris syndrome." (PMID 26376624, 2015).
Nicolaides-Baraitser syndrome (12 papers, 2012 to 2026). "A de novo SMARCA2 mutation was identified and was therefore diagnosed as Nicolaides-Baraitser syndrome." (PMID 32595695, 2020). "Missense mutations or in-frame deletions affecting the ATPase function of SMARCA2 are causative for Nicolaides-Baraitser syndrome, a rare condition characterized by sparse hair, facial and limb abnormalities and intellectual disabilities." (PMID 31406271, 2019). "Nicolaides-Baraitser syndrome (NCBRS) is a neurodevelopmental disorder caused by pathogenic sequence variants in SMARCA2 which encodes the catalytic component of the chromatin remodeling BAF complex." (PMID 31288860, 2019). "Additional resequencing of SMARCA2 in 44 individuals revealed heterozygous mutations in the same carboxy-terminal helicase domain in 36 patients, hereby validating SMARCA2 as the causative gene for Nicolaides-Baraitser syndrome." (PMID 23013645, 2012). "Nicolaides-Baraitser syndrome (NCBRS) is a rare autosomal dominant disease characterized by developmental delay, distinctive craniofacial features, sparse hair, and is caused by de novo mutations in the SMARCA2 gene." (PMID 41497020, 2026).
non-small cell lung carcinoma (12 papers, 2016 to 2025). A group of at least three distinct histological types of lung cancer, including non-small cell squamous cell carcinoma, adenocarcinoma, and large cell carcinoma. "Core subunits of the BAF complex, SMARCA4 (encoding BRG1) and SMARCA2 (encoding BRM), are highly homologous, with mutations or deletions closely associated with various tumors, including 10% of non-small cell lung cancers." (PMID 40661782, 2025). "SMARCA2 has become an appealing synthetic-lethal therapeutic target for various cancers, including non-small cell lung cancer (NSCLC), as mutational loss of SMARCA4 in many cancers leads to a functional dependency on residual SMARCA2 activity 22–25." (PMID 38755248, 2024). "Early preclinical studies suggested that SMARCA4-mutated tumors (such as non-small cell lung cancers) were critically reliant on the SMARCA2 paralog." (PMID 32575483, 2020). "Previous studies have documented SMARCA2 mutations or deletion in 5-10% of non-small-cell lung carcinoma, 10% of esophageal adenocarcinoma, 5-9% of gastric cancer, 1.3% of colorectal carcinoma, 3% of clear cell renal cell carcinoma, and 5% adenoid cystic carcinomas." (PMID 41170461, 2025). "A loss of both SMARCA4 and SMARCA2 has been found in 10–26% of non-small cell carcinomas." (PMID 36178285, 2023). "Previous studies have shown that SMARCA2 has a significant effect on the responsiveness to radiotherapy in non-small cell lung cancer, and its depletion can increase the sensitivity to radiotherapy, suggesting that SMARCA2 may be a potential therapeutic target for sensitization to radiotherapy." (PMID 40530955, 2025). "In Small Cell Carcinoma of the Ovary, Hypercalcaemic Type (SCCOHT) and Non-Small Cell Lung Cancer cell cells, SMARCA4 and SMARCA2 acted as tumor suppressors." (PMID 28445125, 2017).
BAFopathy (8 papers, 2021 to 2024). Disorder caused by mutations in the various subunits composing the BAF complex. "Studies have shown that DNAm profiles at subsets of CpGs overlap between individuals with BAFopathies carrying variants in SMARCA2 that cause NCBRS, and in ARID1B, SMARCB1, and SMARCA4 that lead to Coffin-Siris syndromes type 1, 3, and 4, respectively." (PMID 35361921, 2022). "Among the most prominent and most studied BAFopathies are the clinically overlapping syndromes CSS and Nicolaides-Baraitser (NCBRS) (MIM: 601358), caused by variants in BAF complex proteins: ARID1B in CSS1, SMARCB1 in CSS2, and SMARCA4 in CSS4; and SMARCA2 in NCBRS." (PMID 38751117, 2024). "Other combined episignatures, such as for the BAFopathy (genes: ARID1A, ARID1B, SMARCB1, SMARCA2 and SMARCA4) episignature, are already proving their clinical utility." (PMID 38787418, 2024). "We detected a predominantly hypermethylation profile; the highest percentage of overlap in DMPs was with BAFopathies (11%, including ARID1A, ARID1B, SMARCB1, SMARCA2, SMARCA4), and CHARGE syndrome (10%, CHD7)." (PMID 38351292, 2024). "BAFopathy presented with a ~4% overlap, including ARID1A, ARID1B, SMARCB1, SMARCA2, and SMARCA4, and includes several neurodevelopmental disorders caused by variants in genes within the BRG1/BRM-associated factor (BAF) complex." (PMID 37762546, 2023). "This analysis showed that TRIP12 is most closely related to the CSS9 (SOX11), BAFopathy (ARID1A, ARID1B, SMARCB1, SMARCA2, SMARCA4) and MRD23 (SETD5) episignatures." (PMID 36430143, 2022). "Notably, JARID2 exhibited the highest overlap with CHARGE (~7%, CHD7), BAFopathy (~4%, including ARID1A, ARID1B, SMARCB1, SMARCA2, SMARCA4), and the PCR2 complex, which houses Cohen–Gibson syndrome (COGIS) and Weaver syndrome (WVS) (~4%, EED, EZH2)." (PMID 37762546, 2023).
Intellectual disability (8 papers, 2019 to 2023). "SMARCA2-ATPase mutations result in severe intellectual disability cases of NCBRS, but SMARCE1-HMG and DPF2-PHD mutations are correlated to moderate-severe and mild intellectual disability phenotypes, respectively." (PMID 37500730, 2023). "This is also the first reported disease‐causing variant located in the QLQ domain of the SMARCA2 protein associated with intellectual disability, early‐onset epilepsy, and autistic features, suggesting the importance of the high conservation and functional role of this motif." (PMID 34296532, 2021). "Heterozygous missense mutations in SWI/SNF-related matrix associated, actin-dependent regulator of chromatin, subfamily A, member 2 (SMARCA2) cause Nicolaides–Baraitser syndrome, characterized by distal-limb anomalies, distinctive facial morphology, intellectual disability, and sparse hair." (PMID 36032672, 2022).
malignant rhabdoid tumor (8 papers, 2014 to 2025). "PFI-3 is a selective, potent, and cell-permeable SMARCA2/4 bromodomain inhibitor that has been previously characterized in the setting of various cancers (e.g., lung cancer, synovial sarcoma, leukemia, and rhabdoid tumors)." (PMID 36844227, 2023). "Concomitant loss of SMARCA4 and SMARCA2 expression is also a feature of SMARCA4-deficient thoracic sarcomas (SMARCA4-DTS) and of a subset of malignant rhabdoid tumors (MRTs)." (PMID 32575483, 2020). "In particular, in malignant rhabdoid tumor cell lines, increased binding of epigenetic silencers HDAC9 and MEF2D at SMARCA2 promoter sites has been associated with such heterozygous polymorphisms." (PMID 32575483, 2020). "Acase report on the long-lasting response of Pembrolizumab showed that a 58-year-old woman diagnosed with a SMARCA4-deficient malignant rhabdoid tumor-like tumor, characterized by dual loss of SMARCA4 and SMARCA2 on IHC had remarkable symptomatic recovery from the treatment." (PMID 34440689, 2021). "Similar non-mutational SMARCA2 silencing has been also found in concomitant deficiency with SMARCB1 in malignant rhabdoid tumors." (PMID 34440689, 2021). "SMARCA2 in esophageal, SMARCB1 in malignant rhabdoid tumor and epithelial sarcoma, and PBRM1 in kidney cancer are collectively mutated and reported." (PMID 36844227, 2023).
leukemia (7 papers, 2018 to 2025). A malignant (clonal) hematologic disorder, involving hematopoietic stem cells and characterized by the presence of primitive or atypical myeloid or lymphoid cells in the bone marrow and the blood. "BRG1 ATPase is a unique site of assembly for SWI/SNF-like BAF complexes produced in leukemia, whereas BRM (encoded by SMARCA2) is the primary ATPase expressed in quiescent long-term repopulating haematopoietic stem cells (HSCs)." (PMID 39187513, 2024). "SMARCA2 mutations of unknown effect were also found in leukaemia." (PMID 31722744, 2019). "In summary, during lymphocyte differentiation, SMARCA4 and SMARCA2 affect lymphocytic function and the development of related diseases, especially leukemia and lymphoma, by enhancing chromatin accessibility and interacting with various TFs." (PMID 40342423, 2025). "In leukemia, the core ATPase subunits are BRG/SMARCA4 and BRM/SMARCA2, where BRG/SMARCA4 is essential for the proliferation of both normal hematopoietic stem cells and leukemia stem cells." (PMID 29298978, 2018). "The BAF complex, driven by BRG1 (SMARCA4) or BRM (SMARCA2), enables transcription factors such as PU.1 and MYC to bind enhancers and promoters, sustaining oncogenic transcriptional programs essential for leukemia cell survival." (PMID 39682203, 2024).